G6PD (glucose-6-phosphate dehydrogenase)
Diseases named in the same sentence as G6PD in open-access papers (continued):
Sharing a sentence is not in itself a finding about the gene and the disease.
malaria (continued). "They concluded that the G6PD status of an individual is not static and, therefore, the risk of drug-induced haemolysis in malaria cannot be predicted by enzymatic activity far from the acute episode (i.e. during aparasitaemia)." (PMID 38725027, 2024). "A single low dose (0.50 mg/kg) of PQ was haematologically safe in this population of G6PD-deficient African males without malaria." (PMID 38773528, 2024). "The parameters with the largest impact on results across all municipalities were the severity and mortality due to vivax malaria, life expectancy, the lifetime and number of semiquantitative G6PD machines needed, and the costs of G6PD test strips and malaria episodes." (PMID 38194420, 2024). "The HCPs most involved with malaria diagnosis, such as biochemists and microscopists, considered the practical classes essential for learning and were confident in performing the quantitative G6PD test after training." (PMID 38837977, 2024). "Beyond RBC biology and malaria, investigators have also examined the function of G6PD in immunity." (PMID 38938571, 2024). "Sensitivity analyses restricting inclusion to patients with G6PD activity of 30% or higher measured at the time of the acute malaria episode showed similar results to the analysis including patients with G6PD acitivity of 30% or higher measured at any time (appendix pp 30–31)." (PMID 37748497, 2024). "A malaria official and healthcare provider also mentioned (po4, rh3) occasions when patients were tested for G6PD, but after they were tested, the patients decided that they did not want the radical cure treatment because it “wastes their time to earn money or to work” (rh3)." (PMID 39028699, 2024). "This operational study used retrospective patient data from SIVEP-Malaria to investigate whether P vivax patients aged at least 16 years were treated or not treated appropriately with tafenoquine following quantitative G6PD testing." (PMID 38365417, 2024). "36.62% (26/71) of malaria patients were found to carry seven G6PD genotypes." (PMID 38308253, 2024). "In malaria-negative samples, 22 samples (14 males and 8 females) were G6PD deficient and 60 samples (15 males and 45 females) were G6PD intermediate." (PMID 38308253, 2024). "Genetic testing revealed G6PD mutation frequencies of 36.62% in malaria-positive samples and 50.74% in malaria-negative samples." (PMID 38308253, 2024). "Malaria transmission modelling has demonstrated the potential impact of semiquantitative glucose-6-phosphate dehydrogenase (G6PD) testing and treatment with single-dose tafenoquine for Plasmodium vivax radical cure but has not investigated the associated costs." (PMID 38194420, 2024). "A single low-dose of PQ was haematologically safe in this population of G6PD-normal and G6PD-deficient African males without malaria." (PMID 38773528, 2024). "Some genetic variations, such as those found in the hemoglobin subunit beta (HBB), ABO blood group (ABO), ATPase plasma membrane Ca2+ transporting 4 (ATP2B4), glucose-6-phosphate dehydrogenase (G6PD) and CD40 ligand (CD40LG) loci, have been associated with attenuation of severe malaria." (PMID 36895563, 2023). "Considering the 2022 Korean guidelines for hemolytic anemia and malaria management, which emphasize the importance of G6PD tests, this study provides basic information for the transition period of clinical guidelines assessing G6PD deficiency anemia for strategic public health programs in Korea." (PMID 37176619, 2023). "Furthermore, children with G6PD genotype AA were less likely to develop malaria compared to A-A- (aOR: 0.56, 95% CI: 0.32—0.96, p < 0.05)." (PMID 36959634, 2023). "Whether an intervention such as G6PD testing is considered cost-effective will also depend on the budget available, which could be a national health budget or a budget specifically for malaria control." (PMID 37242320, 2023).
malaria (continued). "Because routine G6PD testing is often unavailable in malaria-endemic countries, most national malaria control programs currently recommend a total dose of 3.5 mg/kg administered over 14 days, allowing the daily dose to be reduced to 0.25 mg/kg to minimize hemolysis." (PMID 37604475, 2023). "In the context of resource-constrained settings, point-of-care quantitative G6PD analysis is highly beneficial, as it can be readily used at the same health-facility level where malaria cases are routinely managed, for prompt and better-informed treatment options." (PMID 37127600, 2023). "The quantitative or qualitative G6PD tests that are easy to use and at a cost comparable with the reference spectrophotometry assay or malaria RDT, respectively, should be deployed in remote endemic areas before radical treatment with primaquine or tafenoquine is prescribed." (PMID 37127600, 2023). "Finally, the feasibility of using the G6PD test at the community level where malaria care-seeking often takes place will be critical to inform adoption strategies and scale." (PMID 37824592, 2023). "We describe a case of severe hemolysis occurring after a total dose of 2.04 mg/kg of primaquine used for prophylaxis in a young, G6PD-deficient (Kaiping variant), Australian man without malaria." (PMID 36509054, 2023). "Overall, the lack of protective association of the G6PD genotypes could suggest that the mechanism of protection of G6PD in malaria might differ from that in viral infections." (PMID 37340364, 2023). "GPDH and G6PD, which are involved in glycolysis, electron transport, glycerophospholipids metabolism, the hyperosmotic stress response, and anti-oxidative damage, play important roles in Giardia and Malaria." (PMID 37375084, 2023). "In the current context of Lao PDR, adding supervised PMQ treatment to the G6PD test strategy should be a natural thing since there are pre-existing village malaria volunteers who provide routine malaria testing and treatment services in moderate and high malaria burden villages." (PMID 35468145, 2022). "The staining agent, DRAQ5, stains malaria parasite DNA irrespective of species, and RBCs are distinguished solely by phenotypic G6PD activity, irrespective of underlying genotype." (PMID 35193663, 2022). "Aim of this study was to assess the impact of acute malaria on G6PD activity." (PMID 35544453, 2022). "A malaria card including G6PD data was given to patients with a malaria-positive thick blood smear." (PMID 36422580, 2022). "Patients diagnosed with P. v infection by Village Malaria Workers (VMWs) were referred to local health centres for point-of-care G6PD testing and initiation of radical cure treatment with 14-day or 8-week primaquine regimens depending on G6PD status." (PMID 36264996, 2022). "Patients with malaria who are G6PD normal will be allocated randomly to one of two arms." (PMID 35585641, 2022). "The FY*BN.01/FY*BN.01, responsible for the Fy(a−b−) phenotype, was observed in one patient (female) with uncomplicated malaria who was not a carrier of the G6PD variants." (PMID 35527254, 2022). "Plasmodium falciparum-infected individuals living in both high and low malaria transmission settings who carry the TNF-α 308 GA genotype are more likely to exhibit symptoms of malaria, whilst those with the B allele of the G6PD gene are likely to remain asymptomatic." (PMID 35291755, 2022). "In 2018, FDA approved tafenoquine (Arakoda) for malaria chemoprophylaxis in nonpregnant women and adults aged ≥18 years who are not G6PD deficient as confirmed by a quantitative G6PD test result." (PMID 36048717, 2022). "Percentage Change (95% Confidence Intervals) in G6PD activity between acute malaria and follow up." (PMID 35544453, 2022). "Wuhan is located at in the mid-latitude region, a middle malaria incidence area, and its G6PD carrying situation may be very rich due to the central location of a transportation hub." (PMID 36212142, 2022).
malaria (continued). "Glucose-6-phosphate dehydrogenase (G6PD) and β-chain of haemoglobin (HBB) deficiencies are more prevalent in malaria-endemic countries and are two of the essential loci conferring resistance to severe malaria in humans." (PMID 35811813, 2022). "Our present study has two aims: (i) first, to investigate the prevalence of key malaria-protective polymorphisms in G6PD and HBB genes in the Senegalese population, (ii) secondly, we will check the correlation between main polymorphisms in HBB and G6PD genes and severe malaria outcome." (PMID 35811813, 2022). "G6PD and malaria were found to be more among males than in females." (PMID 36384674, 2022). "However, after adjusting for Hb concentration in the multivariable analysis the estimated changes in G6PD activity levels between the acute malaria episode and follow-up were still apparent." (PMID 35544453, 2022). "When comparing both measurements, G6PD activity was 10% higher during malaria." (PMID 35544453, 2022). "Most evidence has focused on well-established examples, such as the sickle-cell trait protecting against severe malaria in individuals heterozygous for the beta-globin (HBB) sickle-cell allele, glucose-6-phosphate dehydrogenase (G6PD), and the major histocompatibility complex (MHC) region." (PMID 35494225, 2022). "Tafenoquine, though recently approved for malaria radical cure and prophylaxis, still suffers from significant liability and is not recommended for G6PD-deficient individuals." (PMID 33922294, 2021). "First, these data may serve to inform programs and key decision-makers as to the expected usability of a POC G6PD test in the context of malaria case management." (PMID 34238299, 2021). "However, some patients were afraid to suffer finger puncture twice (once for malaria diagnosis and the second time for G6PD when positive for P. vivax malaria)." (PMID 34003840, 2021). "Regardless of G6PD status, acute malaria causes intra- and extravascular haemolysis and, therefore, stimulates erythropoiesis and increases the reticulocyte count." (PMID 34495956, 2021). "During the study, the STANDARD G6PD Test was run over a broad range of operating temperatures, ranging from 17.7°C to 43.7°C, which is representative of true operating conditions for the device in a real-world, malaria-endemic setting." (PMID 34383774, 2021). "Current WHO guidelines for malaria programs are based on the use of primaquine to target hypnozoites; however, routine wide-scale use of a 14-day regimen for a radical cure necessitates G6PD testing whenever possible." (PMID 34699526, 2021). "In 2019, a new medication for chemoprophylaxis tafenoquine (Arakoda) became available in the United States to prevent malaria, which has a weekly dosing schedule for adults who are not pregnant or G6PD deficient." (PMID 33735166, 2021). "The availability of POC G6PD tests represents an opportunity for malaria case management to better align with recommended clinical best practices and provide safer and more effective treatments to all malaria patients." (PMID 34238299, 2021). "In the present study, we found that the protein expression level of Nrf2 and Ho-1 were not significantly changed, indicating that G6pd deficiency mediated malaria resistance is independent of the Nrf2/Ho-1 pathway in the early stage of P.berghei infection." (PMID 34456927, 2021). "In the current study we aimed to evaluate prevalent G6PD genotypes in relation to G6PD activity phenotype in a large sample of females living in a malaria-endemic area of Sumba Island in eastern Indonesia where we have conducted population surveys of G6PD heterogeneity." (PMID 34270547, 2021). "Therefore, this study examined the proportion of G6PDd and the distribution of G6PD genotypes among malaria-infected national groups in Myanmar before initiation of malaria elimination strategies." (PMID 34108049, 2021).
malaria (continued). "We propose that rapid evolution of G6PD may be related to malaria resistance in some special African guenon populations; however, this requires further experimental validation." (PMID 32986826, 2021). "In 2018, FDA approved tafenoquine (Arakoda) for malaria chemoprophylaxis in nonpregnant persons aged ≥18 years who are not G6PD deficient as confirmed by a quantitative G6PD test." (PMID 33735166, 2021). "This is expected given that G6PD is required to protect the RBCs from oxidative stress and this anti-oxidant effect protects against haemolytic anaemia in individuals with HbAA affected by malaria, although reports elsewhere are have been conflicting." (PMID 33461216, 2021). "Potential G6PD test users who provide malaria case management at three sites in Brazil, Ethiopia, and India were trained on the use of the SD Biosensor Standard G6PD Test and assessed based on their ability to understand the test workflow and interpret results." (PMID 34238299, 2021). "Glucose-6-phosphate dehydrogenase (G6PD) enzyme deficiency is the most common enzymopathy in humans, and its distribution has been historically described to be closely associated with that of malaria." (PMID 33214970, 2020). "Therefore, the WHO has recommended that national malaria control programs (NMCPs) should adopt G6PD testing prior to rolling out a PQ-based radical cure." (PMID 33396538, 2020). "The next challenge for rolling out G6PD testing and radical cure is how to communicate these complex concepts to populations whose conceptualization of malaria is different from the biomedical explanation and who also lack the words that would allow accurate translation of the biomedical concepts." (PMID 33396538, 2020). "Improve the value proposition of G6PD testing by considering otherclinical benefits (not only as part of malaria case management) such asaverting exposure to other oxidative agents, improved management of neonatalhyperbilirubinaemia in offspring and averting kernicterus." (PMID 32766454, 2020). "Malaria status was not a significant predictor of G6PD activity irrespective of diagnostic assay applied, however our study was neither designed nor powered to this effect." (PMID 32925910, 2020). "As part of a multi-center project across the region, a mixed-method study was conducted from 2018 to 2019 in a malaria-endemic district of Ninh Thuan to explore the acceptability of radical cure and G6PD testing amongst Ra-glai community members and their healthcare professionals." (PMID 33396538, 2020). "Moreover, the acquisition of relative immunity with age greatly confounds the influence of ABO blood group, G6PD and haemoglobin genotype on malaria." (PMID 32646433, 2020). "However, few studies examined and validated G6PD screening tests at the point-of-care in the village where patients usually seek care for their malaria symptoms." (PMID 32004348, 2020). "However, information regarding G6PD protection from uncomplicated malaria is less clear albeit with a leaning towards protection for female children." (PMID 31941490, 2020). "The exact nature of the selection pressure imposed by malaria at G6PD remains controversial." (PMID 32536341, 2020). "The health and economic advantages of introducing quantitative, point-of-care G6PD testing in malaria case management will be optimised if the clinical benefits of testing can be extended beyond the current primary indication, which is for malaria treatment." (PMID 32766454, 2020). "The syndrome has been associated with SA and positive malaria RDT (despite having negative malaria smears) but not with sickle cell disease or G6PD-deficiency." (PMID 30658602, 2019). "A similar phenomenon was observed in Cameroon with G6PD deficient participants having reduced parasitaemia, lower severity of anaemia and malaria symptoms and higher haemoglobin compared to the non-deficient individuals." (PMID 30819192, 2019).
malaria (continued). "Malaria parasitaemia and demographic features in the G6PD deficient and non-deficient individuals were characterized." (PMID 31590661, 2019). "Females with G6PD A- heterozygotes have been shown with selective advantage against severe malaria." (PMID 31590661, 2019). "When different PQ doses (0.25, 0.4 or 0.75 mg/kg) are given with ACTs, there is a greater initial fall in mean Hb concentrations in both symptomatic and asymptomatic, G6PDd malaria infected patients and G6PDd healthy individuals compared to G6PD normal (n) patients and individuals." (PMID 30871496, 2019). "vivax infected patients with unknown G6PD status from two different countries were prescribed primaquine as per national malaria program guidelines." (PMID 31069260, 2019). "Of 50 G6PD-deficient blood donors, 13 (26%) reported that they had a past history of malaria but were not able to remember the Plasmodium species and treatment they received." (PMID 31525211, 2019). "The limited access to G6PD test and primaquine in rural areas may contribute to delaying elimination of malaria." (PMID 30700970, 2019). "Comparison of frequency (%) of human mutations (G6PD Deficiency, Haemoglobin E, and Haemoglobin Constant Spring) between the general population and malaria patients with and without DPC (n = number of patients)." (PMID 30939179, 2019). "Beyond malaria, G6PD status provides important clinical information for other health conditions that may impact this target group." (PMID 30184203, 2019). "Specifically, it represents a true opportunity to greatly increase access to radical cure of P. vivax malaria, and thus support malaria elimination, and provides an opportunity to address a gender gap in our understanding of G6PD epidemiology and its clinical implications." (PMID 30350771, 2019). "A reliable diagnosis of G6PD status by spectrophotometry is costly, has a turn-around time of several hours, and requires good laboratory infrastructure; limitations that render routine G6PD testing by spectrophotometry unsuitable in most malaria endemic countries." (PMID 30388146, 2018). "However, using PMQ caused substantially greater hematocrit reductions (~8 times the effect of malaria) in G6PD-heterozygous females." (PMID 29889239, 2018). "Glucose-6-phosphate dehydrogenase (G6PD) deficiency is the most common enzymopathy in the human population affecting an estimated 8% of the world population, especially those living in areas of past and present malaria endemicity." (PMID 29738562, 2018). "The Carestart G6PDTM (which is based on G6PD-mediated conversion of a soluble tetrazolium dye to a purple formazan precipitate) has been validated in different settings both in healthy volunteers and in malaria patients." (PMID 29499733, 2018). "For current regimens recommended for radical cure of vivax and ovale malaria, this is unlikely to happen without expanded access to G6PD deficiency testing, patient education on toxicity warning signs, and improved dosage forms for children." (PMID 29672516, 2018). "For example, the absence of G6PD*A− (G202A) and Mediterranean (C563T) mutations was recently reported from blood samples obtained from malaria patients in Southwestern Ethiopia, where 23% of the individuals were noted to carry the G6PD*A (A376G) mutation." (PMID 30367627, 2018). "This was observed in the current study as well, as four of 110 patients with falciparum malaria had G6PD 563c.C>T mutation and were not immune to malaria." (PMID 29065882, 2017). "Thirteen databases were searched for papers reporting any G6PD alteration in malaria patients." (PMID 28382932, 2017). "Finally, G6PD status is important not only in the context of malaria but also in the context of other infections such as typhoid fever and dengue fever, which are prevalent in the GMS." (PMID 29082022, 2017).